MPO (myeloperoxidase)
Diseases named in the same sentence as MPO in open-access papers (continued):
Sharing a sentence is not in itself a finding about the gene and the disease.
colitis (continued). "Four days after acetic acid administration, uniform colitis, a three-fold increase in colonic tissue myeloperoxidase (MPO) activity (an indicator of neutrophil infiltration), and a six-fold increase in plasma exudation occurred." (PMID 38398870, 2024). "In colitis, inflammatory responses lead to the aggregation and activation of neutrophils, resulting in the release of a large amount of MPO." (PMID 38790796, 2024). "During colitis relapse, it improved histological inflammation and biochemically inhibited MPO, alkaline phosphatase, and metalloproteinase 9 activities, while also decreasing MDA and IL-1β levels." (PMID 39494333, 2024). "The reduction in expression level of NLRP3 and its activity was further validated by measuring IL-1β, IL-13, MPO, and NO in colitis-induced mouse model." (PMID 37902927, 2024). "In rats with TNBS-induced colitis, magnolol at various doses significantly reduced colonic MPO activity and serum levels of IL-17." (PMID 39494333, 2024). "Essential oil has been found to reduce histological lesions from colitis and impact the expression of MPO, tumor necrosis factor α, and nuclear factor-κB mucosal mRNA levels." (PMID 38831882, 2024). "In DSS-induced colitis mice, it was demonstrated to exert an anti-inflammatory effect via inhibition of MPO activity and down-regulation of NF-κB and pro-inflammatory mediator secretion." (PMID 39170617, 2024). "Wt-DSS and MPO KO DSS groups yielded similar DAI scores at each phase of colitis induction in the chronic DSS model." (PMID 38673843, 2024). "Our findings point to a dichotomy in the role of MPO during acute colitis and have significant implications for interpreting other disease models of inflammation where MPO plays a pathological role." (PMID 38673843, 2024). "Mice fed leucine-rich diets exhibited comparable colitis symptoms (body weight, colonoscopy, histology, fecal MPO, and gut permeability) compared to their DSS-treated controls." (PMID 39519299, 2024). "DSS-induced colitis was characterized by increased MPO activity (30.09 ± 6.38U for DSS vs 10.11 ± 4.34U for control, p = 0.012), which was significantly inhibited by EMPA (14.29 ± 2.76U, p = 0.038 for 1 mg/kg; 13.69 ± 2.41U, p = 0.036 for 5 mg/kg)." (PMID 37086302, 2024). "In colitis, excessive MPO production can damage the intestinal mucosal barrier, leading to cell damage and the further development of inflammation." (PMID 38790796, 2024). "Caper treatment effectively lowered elevated oxidative stress factors (MDA, NO, and MPO) compared to the control colitis group (p < 0.001)." (PMID 38948035, 2024). "The present investigation confirmed enhanced oxidative stress through significant elevations of colonic NO content and MPO activity in mice with oxazolone-induced colitis." (PMID 37902927, 2024). "The protein levels of MPO, ZO-1, E-cadherin, and occludin were decreased in acute and chronic colitis model mice after LM-CsA NP treatment, and intestinal function recovered after treatment." (PMID 39512421, 2024). "Among C57BL/6 mice subjected to the induction of experimental colitis, the highest MPO activity in the recovery was recorded in the rBL0.1 group." (PMID 38892639, 2024). "DSS‐induced colitis resulted in higher levels of MPO and EPO in the intestine compared to healthy ones." (PMID 39554349, 2024). "In the colitis group, MPO levels were significantly higher than the control group (p < 0.001), and DHA administration significantly decreased the MPO level compared to the colitis group (p < 0.001)." (PMID 39105785, 2024). "HFD feeding resulted in colitis: it elevated myeloperoxidase, TNF-α, IL-1β, and IL-6 levels, NF-κB activation (p-p65/p65), and NF-κB+CD11c+ cell number and decreased IL-10 and SIRT1 levels and AMPK activation (p-AMPK/AMPK) in the colon." (PMID 39599597, 2024).
colitis (continued). "Glabridin ameliorates dextran sulfate sodium-induced colitis in mice by reducing colonic myeloperoxidase activity and the production of inflammatory mediators, such as nitric oxide, prostaglandin E2, and proinflammatory cytokines." (PMID 39086651, 2024). "It was observed that OA inhibited DSS-induced colitis in Th17 cells by suppressing the expression of IL-1, NF-ĸB, MAPK, and RORγt, as well as by inducing the expression of FOXP3, IL-10, and myeloperoxidase, effectively blocking the colitis process." (PMID 39064870, 2024). "The myeloperoxidase enzyme, synthesized in neutrophils with potent antibacterial and antiviral effects, is accepted as the indicator of neutrophil infiltration in colitis." (PMID 39105785, 2024). "The current study aims to examine the impact of PMN MPO on the development of chronic colitis in an experimental mouse model of colitis elicited by repeated induction of DSS colitis." (PMID 39133648, 2024). "During the DSS challenge, neutrophil migration to the inflamed colitis in MPO KO mice significantly increased relative to control counterparts." (PMID 38673843, 2024). "The inflammatory pathway in colitis increases myeloperoxidase (MPO), inducible nitric oxide (NO) synthase, and cox-2 levels, leading to decreased anti-inflammatory proteins and increased pro-inflammatory proteins like IL-6, IL-1B, and TNF-a." (PMID 39668979, 2024). "So we focused on the changes in MPO levels on the pathological response of C. rodentium‐induced colitis in mice in a hypoxic environment." (PMID 38415976, 2024). "In conclusion, in our study, it was thought that arbutin had a protective antioxidant effect on SOD, MDA, and MPO in colitis-induced rats." (PMID 39128087, 2024). "In comparison to treatment with hUC-MSCNC, treatment with hUC-MSCTGFB1 KD did not yield the improvements in body weight, DAI, splenic index and colon MPO levels in colitis mice." (PMID 38956621, 2024). "Accordingly, LAPE was also able to reduce MPO activity, a known marker of neutrophil infiltration in colitis." (PMID 38542183, 2024). "In the same way, celastrol administration has been found to relieve the severity of colitis by decreasing IL-1β, IL-6, myeloperoxidase (MPO), RIPK3, and MLKL levels while increasing active caspase-8 levels and E-cadherin." (PMID 39118979, 2024). "MPO, MDA, TNF-α, and IL-6 levels were elevated in the Colitis group but significantly reduced in the DHA-treated group (p < 0.001 for MPO, MDA; p < 0.05 for TNF-α and IL-6)." (PMID 39105785, 2024). "In contrast, the group treated with Cramp significantly ameliorated DSS-induced colitis, as evidenced by improved weight loss, DAI score, colonic shortening, and MPO activity compared with the DSS group." (PMID 38380090, 2024). "In conclusion, in the C. rodentium‐induced colitis mouse model, MPO can not only affect bacterial clearance but also participate in pathological damage to tissues." (PMID 38415976, 2024). "In the present research study, DCA greatly enhanced antioxidant defense in mice with oxazolone colitis, which was reflected by a significant reduction in NO levels along with MPO enzymatic activity." (PMID 37902927, 2024). "In models of chemically-induced colitis, MSCs have been demonstrated to suppress leukocyte infiltration as indicated by decreased leukocyte counts in the mucosa and submucosa and reduced myeloperoxidase activity." (PMID 38503815, 2024). "There was a significant increase (0.52 ± 0.00) (p < 0.05) in MPO activity in the colitis group compared to the control group." (PMID 39765702, 2024). "As outlined by Yan Ren’s research, MPO expression experiences regulation in Nrf2-influenced colitis mouse models." (PMID 37893693, 2023). "Severe colitis after TNBS enema is followed by body weight loss, diarrhea, and increased myeloperoxidase (MPO) activity in wild-type mice." (PMID 37047397, 2023).
colitis (continued). "Oral gavage of Rd or CK at doses of 1 mg/kg and 5 mg/kg also suppressed IS-induced colitis: their treatments alleviated colon shortening and down-regulated colonic myeloperoxidase, TNF-α, and IL-6 expression, and NF-κB+CD11c+ cell number." (PMID 36926604, 2023). "In a mice model of colitis, supplementation with penta-O-galloyl-β-D-glucose inhibited colon shortening and myeloperoxidase activity, reduced the activation of NF-κB and levels of IL-1β, TNF-α, and IL-6, but increased IL-10 levels." (PMID 36829984, 2023). "Both improved colitis symptoms, downregulated Th1-, 2- and 17-related cytokines, decreased levels of MPO, improved cecal microbiota." (PMID 37485519, 2023). "It was observed that Lactobacillus acidophilus administration reduced colonic MPO activity in the trinitrobenzene sulfonic acid (TNBS) model of rat colitis." (PMID 35838945, 2023). "In this study, we found that the glycated casein by TGase-type group presented remarkably inhibited levels of pro-inflammatory cytokines and MPO activity in serum and colon caused by DSS-induced colitis compared to the casein group." (PMID 37761139, 2023). "To summarize, the LCP diet demonstrated a capacity to inhibit colitis development via diminishing MPO activity and suppressing the expressions of inflammatory cytokines." (PMID 37761037, 2023). "Myeloperoxidase activity, for example, was used as an inflammatory parameter to evaluate the effects of butyrate in a rat colitis model." (PMID 36459573, 2023). "Noticeably, we detected a robust increase in the proportion of neutrophils (CD11b+Ly6G+) driven by C. difficile in mice with colitis, which was further suggested by myeloperoxidase (MPO) staining of colonic tissue." (PMID 36951545, 2023). "On day 3, after colitis induction, significant elevation was demonstrated in the level of MPO and XOR activity and MDA levels relative to the control group values." (PMID 37765297, 2023). "Eudragit RL PO nanoparticles loaded with SM (75 mg/kg/day) can significantly reduce TNF-α, IL-6 and MPO activity in colon tissues, improve macroscopic and histopathological scores of acetic acid-induced colitis mice." (PMID 37033644, 2023). "Combined administration of L. casei and Pistacia atlantica reduced colitis and myeloperoxidase, an enzyme for the detection of neutrophils in colon inflammation, in 2, 4, 6-Trinitrobenzene sulfonic acid (TNBS)-induced ulcerative colitis rats." (PMID 36986118, 2023). "Zinc supplementation has the effect of suppressing colitis in a mouse model, as proved by lessened disease activity and histological severity, as well as decreased myeloperoxidase activity." (PMID 37836377, 2023). "In the present study, we applied immunohistochemistry with mirror sections and double immunofluorescence to demonstrate that uPA was expressed mainly in MPO-positive neutrophils of human colitis tissue." (PMID 36806262, 2023). "EVs derived from human placental MSCs have also been utilised to treat colitis, which markedly reduced intestinal inflammation and oxidative stress by dampening the activity of myeloperoxidase (MPO) and reactive oxygen species (ROS)." (PMID 36849892, 2023). "The colitis model exhibited increased inflammation and tissue damage, as indicated by elevated levels of MPO, colon shortening, and macroscopic colitis scores." (PMID 37904683, 2023). "Reduced severity of the colitis was linked to improved histology scores and reduced colonic MDA and MPO activity." (PMID 37701897, 2023). "Treatment with the essential oil of this plant also decreased the level of myeloperoxidase in colitis." (PMID 37275758, 2023). "Compared with the normal group, with continuous intake DSS, C57BL/6 mice gradually developed colitis with bloody stool, diarrhea, body weight loss, and shortened colon length, showing a significant increase in DAI score and MPO activity (p < 0.01)." (PMID 37375702, 2023).
colitis (continued). "MPO is a pro-inflammatory and pro-oxidative enzyme, which is in direct proportion to the number of neutrophils in colonic tissue of colitis." (PMID 36768559, 2023). "Dietary taurine has been reported to alleviate experimental colitis induced by dextran sulfate sodium (DSS) and trinitrobenzene sulfonic acid (TNBS) in mice and retard weight loss, colon shortening, and myeloperoxidase (MPO) activity elevation." (PMID 37189666, 2023). "We recorded remarkable increase in DAI, histopathologic damage, serum TNF-α and IL-6 levels, and MPO activity in mice with DSS-induced colitis." (PMID 37111064, 2023). "Ergothioneine was previously shown to also demonstrate protective effects against DSS-induced colitis by decreasing MPO activity levels and improving intestinal barrier function." (PMID 37512580, 2023). "Twenty-four hours after colitis induction, significant elevation was demonstrated in the level of MPO and XOR enzyme activity, MDA level and Cytc level relative to the control group values." (PMID 37765297, 2023). "The therapeutic effects of genistein in TNBS-induced colitis were also reported, as accompanied by decreased cyclooxygenase-2 (Cox-2) and MPO levels." (PMID 37298531, 2023). "Compared with the controls, 7-DHC-treated colitis mice showed less body weight loss, lower disease activity index (DAI) scores, longer colons, and lower myeloperoxidase activity, indicating that 7-DHC alleviated experimental colitis with circadian disruption." (PMID 39872859, 2023). "Despite HIF-2α deficiency in all lysozyme M expressing cells (including neutrophils and monocytes/macrophages), this suggests myeloid HIF-2α in the DSS colitis model affects MPO+ neutrophil populations preferably." (PMID 37124241, 2023). "Given that another key aspect of colitis is neutrophil infiltration, the severity of inflammation was further determined by measuring myeloperoxidase (MPO) activity in colonic mucosa from the distal colon." (PMID 37512580, 2023). "-Attenuated severity of colitis.-Decreased colonic MPO activity.-Normalized IL-10 level in colon.-Anti-inflammatory changes in a GPR109a-dependent manner." (PMID 37447318, 2023). "For the sake of exploring the potential pharmacological effects of S. boulardii on inflammation in colitis, MPO, which is a typical inflammatory indicator of colitis reflecting the neutrophil counts, was measured." (PMID 37492256, 2023). "MPO activity is a classic biomarker used to evaluate inflammation in colitis and reflects the degree of neutrophil infiltration." (PMID 37047694, 2023). "In mouse models of colitis, UA administration led to a decrease in the same serum inflammatory markers and colonic neutrophil infiltration attributed to inhibited myeloperoxidase (MPO) activity." (PMID 37508017, 2023). "The flavone, tricin, improved chemically-induced colitis in mice by production in lipopolysaccharides-activated cells and myeloperoxidase activity and regulating gut microbiota profile." (PMID 38196993, 2023). "The repercussion of colitis on the hepatic inflammatory profile was investigated, through MPO activity and TNF-α and IL-10 levels." (PMID 37577725, 2023). "In colitis mice, colon tissue MPO activity was used to detect neutrophil infiltration into the inflamed colon mucosa." (PMID 37438752, 2023). "Compared with the control group, MPO activity greatly increased in the colitis mice but significantly decreased in the PEG-CNPs treatment group, indicating PEG-CNPs reduced the infiltration of inflammatory cells in the colon." (PMID 37507801, 2023). "In a previous study, it was shown that 1,8-cinole decreased MPO activity in trinitrobenzene sulfonic acid (TNBS)-induced colitis in rats." (PMID 37047133, 2023). "Embelin can significantly reduce the DAI score, inflammatory factors, MPO accumulation and further alleviate weight loss, diarrhea, massive hemorrhage and immune cell infiltration in DSS-induced colitis mice." (PMID 37033644, 2023).
colitis (continued). "Fraxinellone, a natural compound isolated from FC, was demonstrated to reduce weight loss and diarrhea in DSS-induced colitis mice, suppress the activities of myeloperoxidase and alkaline phosphatase, and increase the levels of glutathione in colitis tissues." (PMID 37161415, 2023). "Nevertheless, the Chinese medicine Panax notoginseng (Burkill) F.H.Chen can repair vascular damage in experimental colitis by reducing the concentration of MPO to reduce inflammation and oxidative stress in the colonic mucosa (Wang SY." (PMID 35873579, 2022). "In our finding, PYY 3–36 strongly mitigated the loss of body weight, colonic inflammation, and MPO activity and increased the survival rate in mice with TNBS-induced colitis." (PMID 35443853, 2022). "First, oral administration of DCL (5–15 mg/kg) not only ameliorated symptoms of colitis and colonic barrier injury, but also inhibited the expression of proinflammatory cytokines and myeloperoxidase in colon tissues in DSS-challenged mice." (PMID 35321327, 2022). "This group presented moderate DAI, proinflammatory cytokines profile, MPO level, oxidative parameters level, NF-κB expression and Grade II pathological lesion including colitis with showing massive coagulative necrosis of the entire intestinal mucosa." (PMID 36384756, 2022). "Recent studies reported that DSS colitis severity is associated with increased production of various inflammatory mediators such as TNF-α, IL-1β, and MPO activity; and IL-10 and TGF-β drive anti-inflammatory response to prevent colitis." (PMID 36193153, 2022). "Untreated animals suffering from colitis showed a significant higher level of MPO in comparison with healthy rats." (PMID 36203483, 2022). "The activity of MPO in the colitis mice was much more than that in normal mice, and was significantly improved by LUT ​+ ​TPGS-PBTE NPs and LUT@TPGS-PBTE NPs therapies." (PMID 35372817, 2022). "TNBS-induced colitis rats showed significantly increased levels of MPO and MDA and significantly decreased GSH levels in the colon homogenates." (PMID 35239781, 2022). "Treatment with UroA significantly reduced the colonic MPO in in WT mice that were subjected to colitis." (PMID 36159798, 2022). "When comparing the colitis group treated with vehicle and the colitis group treated with HEBD, there is a 50% decrease (p < 0.01) in MPO levels in the colitis group treated with HEBD." (PMID 35295931, 2022). "In comparison to the TNBS colitis group, a significant reduction in MPO levels was observed in the BEY-treated group (p < 0.01)." (PMID 35565934, 2022). "TNBS-treated mice developed a moderate to severe colitis, as evidenced by elevated levels of the clinical activity score, the colon weight/length ratio, myeloperoxidase (MPO) activity and pro-inflammatory cytokines." (PMID 35214083, 2022). "Our data showed that oral administration of DeinoLys attenuated colitis clinical signs, histopathological changes, and colonic MPO level in a DSS-induced colitis mouse model." (PMID 35719091, 2022). "DSS-induced colitis significantly increased the neutrophil marker myeloperoxidase (MPO), but ED treatment decreased it significantly." (PMID 36468853, 2022). "Previous studies have reported that DSS-induced colitis is associated with increased levels of MDA, MPO and NO and our results from current research have replicated these findings." (PMID 36365201, 2022). "EGCG reduced the levels of TNF-α, IL-6, and NF-κB mRNA expression, NF-κB protein, and MPO activity in colon tissue of rats with trinitrobenzene sulfonic acid (TNBS)-induced colitis." (PMID 35807865, 2022). "The activity of MPO was markedly (p < 0.001) increased in the colitis group compared to the control group." (PMID 35566122, 2022). "Neutrophil infiltration leads to remarkable elevation of MPO activity in colon, which is a typical inflammatory marker of colitis." (PMID 36741371, 2022).